IL10 (interleukin 10)
Diseases named in the same sentence as IL10 in open-access papers (continued):
Sharing a sentence is not in itself a finding about the gene and the disease.
cancer (continued). "Furthermore, the increased IL-10 and TNF-α levels lead to a decrease in the lymphocyte count, a crucial component of innate immunity and the adaptive immune response, with a relevant role in the immune surveillance process towards cancer cells." (PMID 29983708, 2018). "The third phase (escape phase) begins when cancer cells become capable of binding and activating the co-inhibitory molecules on the T lymphocytes (CTLA-4, PD-1, LAG-3, TIM-3), and secreting soluble immunosuppressive or inducing the secretion of mediators such as IDO, TGFβ, IL10." (PMID 29492219, 2018). "Patients with active cancer had higher baseline IL-10 levels than those without cancer (p = 0.023)." (PMID 28692671, 2017). "Therefore, therapeutic vaccines containing a IL-10 signalling inhibitor may be effective against chronic HPV infection and HPV infection related cancers in human." (PMID 28810829, 2017). "Furthermore, MSCs can differentiate into cancer-associated fibroblasts (CAFs) that produce high levels of IL-4, IL-10, TGF-β1 and vascular endothelial growth factor (VEGF) and regulate epithelial-mesenchymal transition (EMT) mechanism, thus they support cancer cell survival and metastasis." (PMID 28367424, 2017). "Our results clearly indicate increased levels of IL-10, TNF-α, TGF-β and VEGF both in serum and saliva and they suggest that these cytokines may constitute valuable tools in diagnosis, treatment and prognosis in cancer disease." (PMID 27547238, 2016). "Finally, MPO activity, protein and IL-10 were all altered in BAL fluid of cancer septic mice although this was not accompanied by differences in histologic lung inflammation or other BAL cytokines between previously healthy septic mice and cancer septic mice." (PMID 27018973, 2016). "The same technology could be extended to other types of proteins especially cancer markers such as Ca 15-3, 27, 125, bladder tumor antigen (BTA), carcinoembryonic antigen (CEA), alpha-fetoprotein (AFP), IL-10, as well as small molecules, as long as the required suitable aptamers are made available." (PMID 26102488, 2015). "The function of MDSC is highly depended on the cancer microenvironment and mediates its suppressive activity on the immune system through multiple mechanisms such as the production of ROS, nitric oxide (NO), and arginase (ARG-1) and secretion of the cytokines IL-10 and TGF-β1." (PMID 25436215, 2014). "However, our data suggested that circulating IL-10 and MSLN levels may undergo quantitative change when malignancy had developed compared to normal status." (PMID 24520352, 2014). "Interestingly, the number of CD45RO + TILs in ILT4 or IL-10 positive cancer tissues was less than that of negative groups." (PMID 24762057, 2014). "In addition, the higher ratios of IFNα2 to Th2 cytokines, including IFNα2/IL4, IFNα2/IL10, IFNα2/CCL2, IFNα2/CCL7, IFNα2/CCL11, and IFNα2/TNFα, were associated with increased odds of ER negative vs. ER positive cancer." (PMID 24473087, 2014). "However, M2 ARG1 and IL-10 but not TGF-β expression levels increased with cancer progression." (PMID 40666494, 2025). "These cytokines are associated with immunosuppressive and regulatory functions, so their decrease could promote a better response to cancer treatment, especially IL-10, given its key role in tumorigenesis and its negative correlation with disease-free survival in certain cancers." (PMID 39126001, 2024). "However, the role of IL-10 in cancer is not so straightforward." (PMID 37501757, 2023). "Additionally, FJX1 expression was significantly and positively correlated with immunosuppressive genes (TGFB1 and IL-10), chemokines (CCR1 and CCR5), chemokines receptors (CCL2 and CXCL5), and immunosuppressive pathway-related genes (TFGB1 and WNT1), in most TCGA cancers." (PMID 37324001, 2023).
cancer (continued). "Interestingly, among pan-cancer, LGG showed the most significant correlation between GLA with CD86 (P=4.52e-27), CSF1R (P=8.17e-09),CCL2 (P=3.98e-14), CD68 (P=2.37e-34), IL10 (P=3.29e-21), IRF5 (P=8.5e-25), CD163 (P=3.8e-26), VSIG4 (P=9.17e-16) and MS4A4A (P=1.39e-21)." (PMID 37057282, 2023). "Besides, the addition of the Pegilodecakin (pegylated recombinant human IL-10) or pegylated IFNα-2b (PEG-IFN) to pembrolizumab demonstrated a manageable toxicity profile and preliminary anti-cancer activity in RCC patients mainly by provoking the CTLs anti-cancer activities." (PMID 36510217, 2022). "Interestingly, BMDC exposed to synchronized ferroptotic cancer cells (early, intermediate, late) in contrast to UVB-treated apoptotic cells did not produce substantial amounts of cytokines related to inflammation (IL-6, IL-12, TNF, IFN-β) and adaptive immune response (IL-10, IFN-γ)." (PMID 35760796, 2022). "Thus, IL-10 may not be an ideal target given its pleiotropic effects on NK cells and in the context of cancer." (PMID 34768810, 2021). "However, this elevation of IL-10 may not be high enough to combat cancer, and thus, the authors could have drawn incorrect conclusions about the role played by IL-10 in the immune response against tumors." (PMID 33912464, 2021). "The reason why we did not see a similar IL-10 levels and monocytes relation in ER+ BC even with the same PLX effect may suggest that severity of the cancer and progesterone and ER play a role in plasma IL-10 levels, but this information is not elucidated in this study." (PMID 32733470, 2020). "However, previous cancer in-depth studies have not been carried out using BMSCs modified by IL10." (PMID 32742480, 2020). "Furthermore, tea inhibits the release of antiinflammatory cytokines such as interleukins (IL-6, IL-8, IL-10, IL-12), as well as the receptor activator of nuclear factor kappa-B ligand (RANKL), and acts as an anticancer agent by stimulating apoptotic processes in cancer cells." (PMID 26834707, 2015). "However, in cancers both cellular and humoral immune response may be depressed, as in the absence of IL-4 production IL-10 secretion alone cannot induce a Th2-type response." (PMID 16478542, 2006). "Trials containing IO agents other than PD-L1/PD-1 inhibitors without chemotherapy included agents targeting IL-10 inhibitor, toll-like receptor 9 (TLR9) agonist and cancer vaccines." (PMID 33816286, 2021). "In cancer patients, besides IL-17, Th17 cells produce high levels of other immunological mediators, such as GM-CSF, IL-2, TNF and IFN-γ, but not IL-10." (PMID 34646761, 2021). "Regardless of the specific metabolic control exerted over cancer cells by inflammatory factors during PC, TNF-α, IL6, TGF-β, and IL10 are shared mediators for the initiation and progression of several cancer types." (PMID 34205944, 2021). "According to the literature, CXCL1, IL10 and CCL4 are more or less well described myokines, but as muscle-derived factors no significant anti-cancer effect has been attributed to them yet." (PMID 34359731, 2021). "For example, while neither (mf or cancer cell lines) induces the production of CCL4, TNF-α, IL-10, or VEGF, they both significantly enhance the production of IP-10 and CCL22 in human monocytes." (PMID 29668679, 2018). "Regarding the cytokines evaluated in the serum of individuals with and without cancer, significant differences were observed among individuals with cancer for IL2, IL10, TNF-α, IFN-g and IL17." (PMID 26905729, 2016). "Laricitrin, syringetin, resveratrol, and piceatannol decreased the expression of IL-10 in both A549 and CL1-5-conditioned DCs at the concentration without cytotoxicity for both DCs and cancer cells." (PMID 27833081, 2016). "Cancer tissue from women not infected with HPV 16 or 18 had higher concentrations of GMCSF (p = 0.004), IL10 (p = 0.037), and IL15 (p = 0.041), when compared to those of women infected with HPV16/18, after adjusting for age, parity and hormonal contraception." (PMID 25810759, 2015).
cancer (continued). "In a related study, DCs from cancer patients generated from CD14+monocytes by culturing with GM-CSF and IFN-α, but without IL-4 secreted higher levels of IL-10 (Th2 response), compared with IL-4 and GM-CSF generated DCs." (PMID 18588665, 2008). "Interestingly, when macrophages were cocultured with radioresistant cells, both proinflammatory (CCR7, CD80) and anti-inflammatory markers (IL-10 and CCL18) were overexpressed, with no changes in cancer cell migration and invasion." (PMID 37347290, 2023). "This study included both pro‐inflammatory (IL‐1B, IL‐6, IL‐8, IL‐12 (p40, p70), TNF‐α, and IFN‐γ), and anti‐inflammatory (IL‐4, IL‐6, IL‐10, TGF‐β), peripheral cytokine blood serum markers with no significant findings evident between cancer survivors and matched controls." (PMID 37751068, 2023). "To further investigate the connection between STAT1, STAT3 and said cytokines in drug resistance, we have treated cells (EP and LP) with cytokine-neutralized (IL-6, IL-10 and IL-1β) MDSC supernatant (in presence or absence of these cytokines), keeping untreated cancer cells as a control." (PMID 38304256, 2023). "IL-10 concentrations in BALF from mice with or without LLC cancers were similar, although IL-10 mRNA expression increased by 80- to 150-fold in response to S100A8 and/or growing LLC cancers." (PMID 35655772, 2022). "However, our results showed that, according to the present protocol, cancer induction with DMH and/or NFRFP consumption does not modify serum concentrations of IFNγ, IL-6, IL-10, IL-12p70, MCP-1, and TNF-α." (PMID 34444868, 2021). "Moreover, whereas we identified the effects of the overall inflammatory mediators on cancer incidence through DII, we did not observe the effects of individual inflammatory markers such as hs-CRP, IL-1β, IL-4, IL-6, IL-10 or (TNF)-α." (PMID 31652856, 2019). "IL-30-silenced tumors developed in IL-30KO mice, IL-30−/−tumors, lacked vascular supply and displayed frequent apoptotic cancer cells entrapped by perforin+TRAIL+CD3+Tlymphocytes, most of which had a CD4+T phenotype, whereas IL-10+TGFβ+Foxp3+Tregs were lacking." (PMID 31366386, 2019). "A different population of macrophages was recently identified in persistent LCMV infection resembling the myeloid derived suppressor cell (MDSC) observed in cancer; however, these MDSC-like cells were distinct from DC and macrophages we identified and did not express IL-10 or PDL-1." (PMID 26808628, 2016). "Notably, after knocking down STAT6 in macrophages, the expression of CD206 stimulated by IL-4 was not reduced by 23-HBA, and 23-HBA failed to inhibit the activation of the IL-10/STAT3/Bcl-2 signaling pathway induced by M2 macrophages and the resulting resistance to 5-FU in cancer cells." (PMID 38554148, 2024). "However with the exception of TGF-β, we found no consistent significant increases in IL-10, IL-4, Il-13, Il-6, GM-CSF, G-CSF, or VEGF in the blood that could account for the failure across cancer patients." (PMID 31462392, 2019). "Consequently, the probiotic strain, E. faecium BR0085, showed a good potential to stimulate the cancer killing ability of NK cells and this mechanism may not rely on the production of IFN-γ or IL-10; however, more evidence is needed to support this observation." (PMID 25759833, 2014).
inflammation (286 papers, 2004 to 2026). Aberrant reaction of the microcirculation characterized by movement of fluid and leukocytes from the blood into extravascular tissues. "Characterization of the interleukin (IL)‐10 knockout (KO) mouse with chronic gut inflammation, cardiovascular dysfunction, and bone loss suggests a critical role for this cytokine in interorgan communication within the gut, bone, and cardiovascular axis." (PMID 38217044, 2024). "FB1, as a toxic stimulate factor, can trigger abnormal expression of TNF-α and inflammatory factors, including IL-1β (Interleukin-1 bata), IL-2 (Interleukin-2), IL-4 (Interleukin-4), and IL-10 (Interleukin-10), and cause intestinal inflammation in mice." (PMID 38769285, 2024). "On the other hand, LP-DCs can produce high levels of the immunosuppressive cytokine IL-10, whose genetic defect causes gastrointestinal inflammation in humans and mice, and its induced antitumor effect is mainly dependent on CD8+ T cells." (PMID 36713833, 2023). "It is suggested that dietary folate deficiency further aggravated renal inflammation and suppressed anti-inflammatory cytokine IL-10 secretion." (PMID 37630806, 2023). "These emulsifiers also decreased the level of SCFAs and altered mucus thickness to aggravate intestinal inflammation in interleukin-10 deficient (IL10 KO) and toll-like receptor 5 knockout mice." (PMID 35893902, 2022). "IL-10, an anti-inflammatory cytokine associated with the resolution of neuro-inflammation, was higher in the Probiotic group compared to the Control group." (PMID 35685773, 2022). "Intestinal inflammation in IL-10−/− mice colonized with H. hepaticus is associated with altered gut microbiota." (PMID 34126769, 2021). "This is partially in contrast to an animal model of Se deficiency-induced renal inflammation, where disruption of selenoproteins led to an initiation of the NF-κB pathway with increased IL-6 and reduced IL-10 concentrations." (PMID 34203015, 2021). "In the present study of mice with pulmonary infections of A. baumannii, we showed that IL-10 deficiency resulted in enhanced mortality, severe lung inflammation, and excess production of proinflammatory cytokines and chemokines in lung homogenates." (PMID 32153580, 2020). "Mice lacking either one of these two receptors develop spontaneous intestinal inflammation, alike IL-10-deficient mice, which reveals a key role for IL-10 in controlling inflammatory diseases." (PMID 29016674, 2017). "For these analyses interleukin-10 deficient (Il10tmCgn, Il10-/-) mice were used that developed intestinal inflammation spontaneously in a microbiome dependent manner." (PMID 27191968, 2016). "The finding that IL-10 deficient mice develop spontaneous chronic intestinal inflammation has established a key role for IL-10 in intestinal immune homeostasis." (PMID 26549988, 2015). "This extract, orally administered at 25, 50, or 100 mg/kg at 96, 72, 48, 24, and 2 h before intestinal inflammation induction, showed anti-inflammatory effects associated with increased IL-10 synthesis, reduced oxidative stress, and reduction in the pro-inflammatory cytokines IL-1β, IL-6, and TNF-α." (PMID 37242733, 2023). "A high IL-10/IL-12 ratio is associated with a protective effect against intestinal inflammation." (PMID 37110329, 2023). "Mucin depletion and microbiota refitting—probably related with ERS—in the colon of IL-10 deficient mice are associated with early intestinal barrier dysfunction and precede overt gut inflammation in this animal model of chronic intestinal inflammation." (PMID 36699599, 2022). "The pro-inflammatory cytokines: namely TNF-α and IL-1β, and anti-inflammatory IL-10 are associated with lung inflammation and function, and studies using rodent models found an attenuation of both acute and chronic lung inflammation by polyphenol and anthocyanin intake." (PMID 34959825, 2021).
inflammation (continued). "Moreover, monocytes from preterm infants produce lower levels of IL-10, which is an anti-inflammatory cytokine critical for intestinal homeostasis, increasing the risk of exaggerated bowel inflammation." (PMID 33671220, 2021). "Previous research has shown that IL-10 deficiency may induce intestinal inflammation and chronic intestinal inflammation." (PMID 31217027, 2019). "These cell changes result in enhanced IL-17 and IL-6 expression but reduced Foxp3 and IL-10 expression in the renal tissues of LN mice, which are significant risk factors for the occurrence of renal inflammation and underlying causes for developing renal damage." (PMID 31488076, 2019). "Notably, sensitization of IL-10-deficient mice with OVA/Alum/CpG resulted in the development of neutrophilic lung inflammation associated with IFNγ production." (PMID 28220116, 2017). "On the other hand, we could detect a higher IL-10 in situ expression by cells in LC lesions, associated with necrotic granulomatous inflammation and a tendency of higher number of lesions, longer duration and longer treatment duration." (PMID 27622513, 2016). "For instance, metalloprotease gelatinase E (GelE) secreted by E. faecalis contributes to the development of chronic intestinal inflammation in mice that are susceptible to intestinal inflammation (IL-10−/− and TNFdeltaARE mice) by impairing epithelial barrier integrity." (PMID 26635787, 2015). "IL-10-deficient mice spontaneously develop gut inflammation." (PMID 25110521, 2014). "Interestingly, the alveolar macrophage and monocyte populations had a predominant pro-inflammatory phenotype in mAlum offspring, evidenced by their increase in TNFα production and a parallel decrease in IL-10, a phenotype implicated in orchestrating and exacerbating pulmonary inflammation." (PMID 37646035, 2023). "Similar patterns have been reported in chronic endometrial inflammation models, where initial IL-10 increases serve to limit tissue damage." (PMID 41298316, 2025). "Studies have shown that helminths can induce IL-10 to suppress Th2-driven airway inflammation, which aligns with their ability to persist within hosts while mitigating excessive immune responses." (PMID 39806495, 2025). "Studies found that altered flora in patients with neonatal necrotizing small bowel colitis led to significant intestinal inflammation, resulting in increased expression of IL‐1, IL‐2, IL‐4, IL‐6, IL‐8, IL‐10, TNF‐α, IFN‐γ, and IL‐17 in samples." (PMID 40119640, 2025). "Leukocyte counts, C-reactive protein (CRP), interleukin-6 (IL-6), interleukin-10, and tumor necrosis factor-α (TNF-α) are the markers used in most studies that are determined to be associated with low-grade chronic inflammation." (PMID 40332421, 2025). "Cytokine profiling revealed distinct signatures: IL-10 was markedly elevated in severe cases, particularly in patients with pulmonary inflammation and in complicated cases beyond day 25, consistent with an anti-inflammatory counter-regulatory response." (PMID 41157211, 2025). "Together, our results suggest that ICOS deficiency promotes IL-10 production in ILC2s and that IL-10 plays a role in regulation of ILC2-induced AHR and lung inflammation in ICOS-KO mice." (PMID 40627441, 2025). "Subchronic treatment of rats with E. crinita alginate at doses of 25 mg/kg and 100 mg/kg bw did not significantly change serum levels of the anti-inflammatory cytokine IL-10 in a model of LPS-induced systemic inflammation in comparison to controls." (PMID 39590762, 2024). "Simultaneously, the female immune system actively responds to acute WS exposure, resolves lung inflammation, and consequently leads to a significant decrease in the concentrations of IL-6 and IL-10 BAL cytokines." (PMID 38797836, 2024). "The study finally showed that when the level of IL‐10 was reduced, airway inflammation was aggravated, especially the accumulation of macrophages and neutrophils in the inflammatory response triggered by LPS was enhanced." (PMID 39090662, 2024).